IL10 (interleukin 10)
Diseases named in the same sentence as IL10 in open-access papers (continued):
Sharing a sentence is not in itself a finding about the gene and the disease.
tumor (continued). "It is possible that the tumor suppressive phenotype observed in the PyMT/p11-KO mice is ascribed to the increase in tumor suppressive cytokines such as Il-10 and Ifn-γ." (PMID 33297495, 2020). "M2 macrophages promote tumor growth, progression, invasion and metastasis by producing anti-inflammatory cytokines, such as IL-10 and TGF-β." (PMID 33479597, 2020). "IL-10 promotes tumor immune escape by inhibiting the function of APC, Th1 cells, NK cells, and macrophages." (PMID 33204731, 2020). "M1 secretes gamma interferon (IFN-훾) and other inflammatory cytokines, whereas M2 produces immunosuppressive cytokines such as interleukin 10 (IL-10) that participates in the tumor immune escape in the TME and promotes tumor cell proliferation." (PMID 31771616, 2019). "The regulatory B (Breg) cell subset producing high levels of IL-10 is known to accumulate in tumor environment." (PMID 31181729, 2019). "Purified astrocytes from tumor specimens revealed a reactive state marked by IL10 and IFNγ response resulting in a JAK/STAT pathway activation." (PMID 31186414, 2019). "MDSCs inhibit the ability of other immune cells to kill tumor cells by producing soluble factors such as interleukin (IL)-10, transforming growth factor-β (TGFβ), arginase 1 (Arg1), and reactive oxygen species (ROS) as well as by direct cell:cell interactions." (PMID 31781510, 2019). "B regulatory cells (Bregs), a subset of B cells, and tumor-associated macrophages (TAMs) reduce the activity of cytotoxic CD8+ and CD4+ T effector cells by releasing anti-inflammatory cytokines like IL-10 and by expressing coinhibitory molecules." (PMID 31949880, 2019). "Suppression of the immune response by inhibiting the T helper cells (Th1) response is considered the main mechanism proposed for the IL-10 to promote tumor growth in humans." (PMID 30814315, 2019). "The authors reported a delay in tumor growth, an influx of lymphocytes and NK cells into the tumors, and, in the tumor microenvironment, reduced levels of the suppressive cytokines IL-10 and TGFβ, and increased levels of IL-2 and TNFα." (PMID 31588231, 2019). "Other studies show significant correlations between IL-10 and aggressive tumor characteristics; however, some studies reported a protective association of IL-10 on cancer survival." (PMID 31448052, 2019). "TGF-β2, along with IL-10, is a prototypical mediator of tumor-induced immune suppression and T-reg induction, and introduction of TGF-β2 antisense plasmid was shown to increase vaccine immunogenicity in preclinical studies." (PMID 30723469, 2019). "STAT3-activating cytokines such as IL-6 and IL-10 are found in abundance within the tumor microenvironment." (PMID 31766350, 2019). "The milieu of cells in the tumor microenvironment produces cytokines such as IL-4, IL-10, IL-13, and M-CSF that encourage M2 or immunosuppressive phenotype differentiation." (PMID 30931508, 2019). "The possible explanation was that up-regulation of IL-10 not only promoted tumor cell growth rate and migration capability, but also suppressed T-cell immunity, leading to a persistent HPV infection and the progression of HPV-positive OSCC." (PMID 31001266, 2019). "Compared with those from the vector‐NC group, the expression of IFN‐γ and IL‐2 was decreased and the expression of IL‐10 was increased in the tumor tissue samples from the MACC1 group; this difference was significant (P < .05)." (PMID 31557409, 2019). "In contrast, M2 macrophages act as anti-immunogenic cells that express anti-inflammatory cytokines such as IL-10 and TGFβ, which subsequently inhibit the function of effector T cells and hence favor tumor progression." (PMID 31455032, 2019). "They showed how this Breg subset is able to suppress T-cell specific antitumor response and to promote tumor development through IL-10 signals." (PMID 31086070, 2019).
tumor (continued). "Second, the failure of IL-10 production by mouse DCs in tumor tissues in response to CT would also reduce the level of immunosuppression in the tumor microenvironment, since IL-10 is a potent immunosuppressive cytokine." (PMID 30972427, 2019). "Immunoregulatory tumor infiltrating B cells (Bregs) have been shown to inhibit anti-tumor T cell responses in some models through IL-10 production." (PMID 31200747, 2019). "On one hand, IL‐10 as well as IL‐6 were confirmed as negative regulators for innate immune cells that destroy the immunity to tumor cells." (PMID 31222971, 2019). "Our previous study on mouse hematologic neoplasm cells indicated that a blockade of ICOS/ICOSL pathways in tumor cells led to the downregulation of IL-4 and IL-10, both of which have anti-inflammatory effects." (PMID 31143539, 2019). "The result clearly showed that immunisation with EX/MPLA/anti-IL-10 antibody plus local administration of caerin peptides significantly increased the survival time of TC-1 tumour bearing mice." (PMID 31277636, 2019). "In WSC group the plasma level of ANGPTL-4 was positively correlated with IL-10 (p=0.04) and IL-15 (p=0.02) in the tumor and with IL-15 (p < 0.01) in the mesenteric adipose tissue." (PMID 31741709, 2019). "M2 macrophages are involved in the enhancement of immunosuppression through the stimulation of Tregs and the secretion of TGF-b, TNF-a, and IL-10, leading to the creation of a favorable tumor microenvironment." (PMID 31510065, 2019). "Our results demonstrate that coculture with H-1299 tumor cells leads to the upregulation of IL-6, IL-10, and IL-27 production by CD1c+ DCs compared with that by CD1c+ DCs that were not cocultured with H-1299 cells." (PMID 31921114, 2019). "In particular, the expression of Ang-2 by tumor cells can induce the recruitment of TIE-2-expressing monocytes (TEM) which in turn are responsible for the release of IL-10." (PMID 31370258, 2019). "It was observed that the number of IL-10-secreting MSCs is significantly lower in tumor from NLGP-treated mice than tumor from mice with PBS treatment." (PMID 31547863, 2019). "In the tumor microenvironment, a variety of inflammatory mediators, such as cytokines (IL-6, IL-10, VEGF, TNFα, and TGFβ), chemokines (CCL20 and CXCL8) as well as lipid mediators (such as PGE2) are continuously produced." (PMID 31100828, 2019). "SKILs were tested for their capacity to produce T helper 1 (Th1) cell cytokines (IFN-γ and IL-2) or T helper 2 (Th2) cell cytokines (IL-5 and IL-10) upon co-culture with the tumor antigen peptides." (PMID 31727154, 2019). "Overexpression of miR-148a promoted the expression of IL-10 and the invasive ability of tumor cells." (PMID 31777603, 2019). "Studies in mouse tumor models have shown that IL-10 can suppress the maturation of intratumoral dendritic cells (DCs) and their production of IL-12, and thereby limits cytotoxic T cell responses during chemotherapy." (PMID 31805946, 2019). "Treatment of IL-10 deficient mice with a pegylated (PEG) form of recombinant human IL-10 increased the cytotoxic activity of CD8+ T cells and controlled tumor growth." (PMID 32039024, 2019). "The functions of these two subsets were different: ICOS+ Tregs secrete much larger amounts of interleukin 10 (IL-10), a critical negative regulator in tumor escape; while ICOS- Tregs have a high capacity for TGF-β expression." (PMID 31777600, 2019). "This suppressive role is of particular importance in the liver, where IL-10 ensures that liver NK cells/ILC1s remain immune-tolerant, but is undesirable in the context of tumor surveillance." (PMID 31781102, 2019). "Essentially, interleukin 6 (IL6) and TGFβ promote tumor growth, IL6 together with TNFα facilitates invasion and metastasis, and TGFβ with IL10 suppresses the immune response against the tumor." (PMID 31921146, 2019).
tumor (continued). "In a glioma mouse model, pDC depletion led to prolonged survival, decreased tumor-infiltrating Treg numbers, and substantially decreased production of IL-10 in the remaining intratumoral Tregs." (PMID 30987228, 2019). "Tumor hypoxia upregulates known inhibitory molecules of the antitumor immune response such as programmed death-ligand 1 (PD-L1), IL-6, IL-10 and indoleamine 2, 3-dioxygenase (IDO)." (PMID 31370258, 2019). "In an animal model blocking IL-10 at the time of E7 long peptide/MPLA immunisation prevents HPV16 E6/7 transformed TC-1 tumour growth." (PMID 30897137, 2019). "Specifically, CD11b+CD103− DC predominate in PDA, express high IL-23 and TGF-β, and induce FoxP3neg tumor-promoting IL-10+IL-17+IFNγ+ regulatory CD4+ T cells." (PMID 30926808, 2019). "TAMs drive tumour progression by secreting anti-inflammatory and immune-modulatory molecules such as IL-10, thus reducing the immune response against cancer cells." (PMID 31480312, 2019). "According to a previous study, tumor progression in NSCLC correlates with tumor-associated macrophages (TAMs), which are regulated by IL-10 and programmed death-ligand 1 (PD-L1)." (PMID 31572178, 2019). "Previously, we demonstrated that blocking the signalling of a cytokine, interleukin 10, at the time of immunisation elicited significantly higher numbers of antigen specific T cells and inhibited tumour growth in mice." (PMID 31277636, 2019). "Secretion of TGF-β and IL-10 from tumor cells and the surrounding environment then promotes macrophage switching to M2 phenotype." (PMID 30931508, 2019). "In contrast to the upregulation of death receptors and NKG2D ligands, cellular stress can induce tumour cells to produce immunosuppressive factors such as IL-10, TGF-β and PD-L1 and these can negatively affect the activation of- and killing by- immune cells." (PMID 30733494, 2019). "We found a small percentage of IL-10+ Bregs within the tumor, however, they seemed to be in the minority, when considering the whole B cell population infiltrating PDAC tumors." (PMID 30972056, 2019). "Conversely, IL-10 has been shown to limit inflammation, stimulate B cells, induce NK cell production of IFN-γ in concert with IL-18, and promote NK cell recognition of tumor cells, allegedly through the IL-10-mediated downregulation of tumor cell MHC." (PMID 31842362, 2019). "Inflammatory Th17 produce IFNγ and IL-17 and exert anti-tumor effects while regulatory Th17 secrete IL-10 and IL-17 and transform ATP into the immunosuppressive molecule adenosine thus sustaining tumor development." (PMID 31024531, 2019). "A similar pattern was observed for IL-10 but the stronger reduction occurred in the HSC3 tumor-bearing mice." (PMID 31572681, 2019). "We further demonstrated in the current study that the DCG administration results in increased levels of IFNγ/IL-10 in the spleen and increased IFNγ/IL-9 secreting T cells infiltrating to the tumour site." (PMID 31183361, 2019). "Both IL-10 and COX-2 are associated with pleiotropic activities in tumor biology and macrophage plasticity." (PMID 30879106, 2019). "IL-10 stimulates PD-L1 expression on DCs or it can suppress DCs anti-tumour function by inhibiting their secretion of IL-12." (PMID 31331034, 2019). "The second wave of increased IL1β, TNFα, and IL6 expression is observed in the 5th day of tumor growth while IL10 second wave occurred two days earlier." (PMID 31712726, 2019). "Tumor-associated macrophages (TAMs) release TGF-β, IL-10, pro-fibrogenic, and pro-angiogenetic factors." (PMID 30723469, 2019). "For example, TEXs isolated from tumor cell supernatants and cancer patients showed a rich expression of FasL, PD-L1, IL-10, TGF-β as well as prostaglandin E2 (PGE2) and ectoenzymes engaged in the adenosine pathway (CD39 and D73)." (PMID 30959898, 2019).
tumor (continued). "These macrophage subset can contribute to cancer progression by producing soluble factors like TGF-β and IL-10 that promote tumor growth and/or help tumor cells evade from host immune surveillance." (PMID 31769418, 2019). "Next, to analyze the immunological changes resulting from administration of the anti-cancer drug in the C57BL/6N mouse stocks, we evaluated the expressions of IL-1β, IL-6 and IL-10 gene isolated from tumor tissue by real-time PCR." (PMID 32257905, 2019). "High levels of IL10 in tumors are generally considered to reflect an immunosuppressive tumor microenvironment, which our presented data on CD163 expression and M2 macrophage polarization supported." (PMID 30879106, 2019). "IL-10 induces tumor growth by: direct stimulation of cell proliferation through an autocrine mechanism and by the induction of angiogenesis and the suppression of the local immune system." (PMID 30814315, 2019). "Tumor cell supernatant from HuCCT1 ICC cell lines induces the production of IL-10 and VEGF-A by macrophages through activation of STAT3 and polarization towards the M2 phenotype." (PMID 31480382, 2019). "Chronic inflammatory conditions promote myeloid cell recruitment to the tumor site where tumor-derived cytokines such as IL-10, TGF-β, GM-CSF, IL-6 initiate their immunosuppressive properties." (PMID 31555270, 2019). "The expression of Th1 cytokines (IL-2, TNF, IFN-γ) and Th2 cytokines (IL-4, IL-5, IL-6, IL-10) were examined in frozen tumor tissues from 80 GC patients by ELISA." (PMID 31417548, 2019). "Cytokines regulating PD-L1 expression, including IFN-g, IL-1a, IL-10, IL-27 and IL-32 g, signal through diverse transcription factors and have variable effects on tumor cells and Monos." (PMID 31730010, 2019). "Interleukin 17A (IL17-A) is classified as an anti-tumor response related cytokine and Interleukin 10 (IL-10) is characterized as an anti-inflammatory cytokine." (PMID 31533251, 2019). "The ELISA quantification data indicated a down-regulation of pro-tumor cytokines (IL-10, VEGF-A, and TGF-β1) and an up-regulation of anti-tumor cytokines (TNF-α, IL-12 p70, and IFN-γ) in the acGM-1.8-treated group." (PMID 31118418, 2019). "In contrast, Il10−/− Egfrwa5/wa5 mice exhibited elevated tumor formation and progression in comparison to Il10−/− Egfr+/+ mice." (PMID 31614493, 2019). "On the contrary, anti-inflammatory ILs (IL-2, IL-12, IL-10, and others) frequently activate antitumor immunity, thus interfering with tumor growth." (PMID 31847214, 2019). "These cells also express cytokines such as IL-10, subsequently aiding in suppression of tumor infiltrating lymphocytes." (PMID 31354741, 2019). "TGF-β1 is produced by multiple cell types within the tumor microenvironment, whereas IL-10 production appears to be restricted to CD4+ T cells." (PMID 31775909, 2019). "Macrophages produce IL-10 and in turn prevent IL-12 secretion of by DCs, resulting in dampened tumor-specific CD8 T cell activation." (PMID 31143179, 2019). "Given the anti-tumor properties of rIL-10, the increased secretion of IL-10 by U937 cells in the presence of vitamin B2, B6 and B9 is likely to be one of the contributing factors to the anti-proliferative/anti-migratory effects noted herein." (PMID 31374832, 2019). "Concomitantly mice carrying metastatic tumours showed an increased serum IL-10/IL-2 ratio (Th2/Th1) after in vivo stimulation with anti-CD3 antibodies." (PMID 31683642, 2019). "Increased cancer cell number and tumor size play an essential role in cancer immunosuppression by producing many immunosuppressive factors such as TGFβ, which then promotes IL-10 production and generation of Tregs and MDSCs." (PMID 30972427, 2019). "IL-10, known to be a potent anti-inflammatory cytokine, can be secreted by almost all immune cells, and by tumor cells." (PMID 30764482, 2019).
tumor (continued). "In the present study, we found that IL-10 protein expression in HCC tissues was significantly higher than that in tumor-adjacent tissues, and IL-10 mRNA levels in HIG2-silenced HCC cells were significantly decreased." (PMID 31142329, 2019). "CXCL8 also recruits MDSCs that inhibit anti-tumor T cell function via the induction of Tregs and production of immunosuppressive cytokines including IL-10 and transforming growth factor beta (TGF-β)." (PMID 30870978, 2019). "Of note, these cells are characterized by the expression of PD-L1 and they promote tumor growth through IL-10 production and PD-L1/PD-1 axis activation." (PMID 31484464, 2019). "STAT3 phosphorylation is considered to be driven by inflammatory and immunosuppressive cytokines and growth factors produced by both tumor and tumor-infiltrating cells including IL-6, IL-10, or VEGF-A." (PMID 31781102, 2019). "Based on our study results, we support the anti-inflammatory effects of the cytokines and we think that by inhibiting the secretion of proinflammatory cytokines IL-10 and IL-4 will contribute to tumor suppression." (PMID 31351482, 2019). "These extracellular vesicles also boost an immunosuppressive state by inducing mediators such as IL-10 in macrophages or by eliciting the expression of PD-L1 in tumor cells." (PMID 31697737, 2019). "The tumor suppressor, programed cell death 4 (Pdcd4), inhibits the translation of Il10 transcripts and the secretion is enhanced in splenocytes in Pdcd4 knockout mice." (PMID 30816218, 2019). "The induction of interleukin-6 (IL-6), IL-10 and colony stimulating factor 1 (CSF-1) contributes to the proliferation and invasion of tumor cells and thereby displays a pro-tumorigenic role." (PMID 31455032, 2019). "In tumor microenvironment the intruding macrophages are modified to suppress IL-12 expression and enhance IL-10 expression." (PMID 31479484, 2019). "Circulating IL-6, IL-8, and IL-10 levels were concomitantly decreased along with tumour shrinkage after 24 weeks of treatment." (PMID 30922248, 2019). "Meanwhile, the downregulation of PDL1 expression increased IFN‐γ, IL‐2, and TNF‐α expressions in mouse serum and tumor tissue samples and decreased IL‐10 expression." (PMID 31557409, 2019). "Irrespective of the mechanism, B lymphocyte function appeared to be attenuated in a tumor microenvironment rich in IL-10 or PTGS2, coding for COX-2, or to a lesser extent also CD163." (PMID 30879106, 2019). "These cells maintain a phenotype similar to in vitro M2 macrophages and contribute to the suppressive tumor microenvironment primarily via expression of anti-inflammatory mediators such as IL-10, TGF-β and IDO." (PMID 31143179, 2019). "Cytokines were measured in the BAL supernatant, and an increase in IL6 and IL10 content was observed in the 7 d tumor group." (PMID 31712726, 2019). "Tumor-derived factors like IL-10 and IL-4 inhibit the production of pro-inflammatory cytokines and chemokines in macrophages and create an immunosuppressive M2-like phenotype resembling TAM." (PMID 31138333, 2019). "In the tumor mass, it is possible to detect an increase in the expression of IL1β, TNFα, and IL10 24 h after its inoculation, whereas IL6 expression increased earlier, just 12 h after cells injection." (PMID 31712726, 2019). "Secretion of certain cytokines from tumor cells, particularly interleukin- (IL-) 6, IL-10, and TNF-α, renders them resistant to the cytotoxic effects of chemotherapeutic drugs." (PMID 31886296, 2019). "Increased IL-10+ B cell numbers in tumor tissues can also be accompanied by increased numbers of CD4+CD25+/highCD127low/− and Foxp3+ Tregs9–12, which are independently associated with tumor progression or reduced patient survival." (PMID 31519915, 2019). "Consistently, in B16F10 tumor-bearing mice, the frequency of IL-6+, IL-21+ and IL-10+ CD4+ T cells in the draining lymph node and spleen were also increased." (PMID 31300052, 2019).